ZBP1 (Z-DNA binding protein 1)
Diseases named in the same sentence as ZBP1 in open-access papers (continued):
Sharing a sentence is not in itself a finding about the gene and the disease.
viral infection (continued). "We and others proposed that Z-RNA is recognized by ZBP1 in settings of viral infection and autoinflammation, resulting in the induction of programmed cell death." (PMID 34525337, 2021). "ZBP1 is a host protein that was shown to be an innate sensor of viral infection, regulating cell death, inflammasome activation, and proinflammatory responses in a variety of situations, including infection and embryonic development." (PMID 32969837, 2020). "Recent research examining intrinsic immune responses to viral infection has demonstrated the nucleic acid sensing-protein ZBP1 as a key initiator of a variety of cell death pathways in response to MCMV, HSV-1, and IAV." (PMID 32649716, 2020). "Previous reports describing ZBP1 induction of apoptosis in response to viral infection have indicated that, depending on cellular conditions, cell death can proceed in both a RIPK3-dependent and RIPK3-independent manner." (PMID 32649716, 2020). "Following viral infection or the ligation of pattern recognition receptors, ZBP1 and TRIF interact with RIPK3 through their RHIM domains to initiate the necroptotic process." (PMID 31922095, 2019). "Most studies on necroptosis have been performed after TNF, FAS, or TLRs stimulation, but it can also be triggered by intracellular events, such as viral infection through Z-DNA or Z-RNA sensing via Z-DNA binding protein 1 (ZBP1/DAI)." (PMID 31164887, 2019). "Double-stranded RNA, typically associated with viral infection, potently activates Type I IFNs via innate immune receptors, such as melanoma differentiation-associated protein 5 (MDA5), protein kinase R (PKR) and Z-DNA binding protein 1 (ZBP1)." (PMID 39126156, 2025). "To explore whether the essential role of RIPK1 in ZBP1 activation during viral infection involves TNF signaling, we treated HT29-hZBP1 cells with or without TNF-neutralizing antibody during HSV-1(ICP6mut) infection." (PMID 39982916, 2025). "In response to viral infection, high expression of Zbp1 is closely related to RIP3 activation, which may trigger the apoptosis and necroptosis of cell." (PMID 39853924, 2025). "ZBP1 functions as a crucial PANoptotic sensor in reaction to viral infections." (PMID 40422233, 2025). "Notably, the Zα2 domain of ZBP1 acts as a molecular switch for triggering PANoptosis upon viral infections." (PMID 38932258, 2024). "Virus infection-induced ZBP1 activation needs ZBP1 to sense the virus-derived Z-RNA." (PMID 38952452, 2024). "Therefore, we examined the interactions between RIPK3 and ZBP1 or Caspase-8 during viral infections." (PMID 39475237, 2024). "Intriguingly, the FRAP experiment verified that ZBP1-Zαβ condensate showed substantial recovery ability after bleaching during virus infection, indicating that ZBP1-Zαβ could form LLPS with Z-NA derived from viruses." (PMID 38982083, 2024). "ZBP1 is a major inducer of necroptosis in response to infection by influenza A virus, herpesviruses, and poxviruses (such as vaccinia virus), and functions in both nuclear and cytoplasmic compartments to mediate necroptosis induced by virus infection." (PMID 39614405, 2024). "ZBP1 has since been demonstrated to mediate necroptosis activation during viral infections." (PMID 39345610, 2024). "ZBP1 plays an important role in viral infections by inducing necroptosis and apoptosis that act to restrict viral replication but may also cause tissue damage and result in pathology." (PMID 39300211, 2024). "Other molecular pathways that can lead to the stimulation of RIPK3 and subsequent necroptosis are the activation of interferon γ-receptors (IFN-γ), toll-like-receptors 3 and 4 (TLR3/4), as well as viral infections leading to activation of the Z-DNA binding protein 1 (ZBP1)." (PMID 39062119, 2024). "ZBP1 is also a crucial regulator of the NLRP3 inflammasome in response to viral infection." (PMID 39475237, 2024).
viral infection (continued). "Z-DNA-binding protein 1 (ZBP1, also known as DAI), which was originally identified as a DNA sensor regulating type I IFN response to synthetic DNA, has been more implicated as an RNA sensor, initiating cell death pathways in response to viral infection." (PMID 39143032, 2024). "Thus, the species of virus and the phase of infection should be considered when evaluating the role of ZBP1 in viral infections." (PMID 38932258, 2024). "Moreover, IRF1 is a positive regulatory factor for ZBP1, and it positively regulates ZBP1 expression during virus infections." (PMID 38129399, 2023). "ZBP1 sensing of virus infection can induce pyroptosis, apoptosis, and necroptosis (PANoptosis)." (PMID 37090158, 2023). "Recently, ZBP1 was identified as an important sensor of necroptosis during virus infection." (PMID 36615244, 2022). "For a long time, studies have focused on the role of ZBP1 in sensing viral nucleic acid in virus-induced cell death, but whether ZBP1-mediated cell death in non-viral infections can detect endogenous ligands remains to be explored." (PMID 36615244, 2022). "ZBP1 is known to interact with RIPK3 to mediate viral infection-induced necroptosis." (PMID 33976222, 2021). "Therefore, ZαE3L likely plays a role in competitive inhibition for Z-DNA/Z-RNA binding antagonizing the function of ADAR1p150 and ZBP1 during virus infection." (PMID 33613567, 2020). "In addition to its role during virus infection, ZBP1 has been shown to activate RIPK3/MLKL-mediated necroptosis in cells lacking RIPK1." (PMID 31786265, 2020). "ZBP1 has also been shown to be involved in IFN induction after virus infection." (PMID 31572318, 2019). "We initially wished to confirm the role of ZBP1 in cell death upon virus infection." (PMID 28716805, 2017). "However, unlike in viral infection, deletion of ZBP1 in our fungal model did not result in a complete loss of CASP1 activation, GSDMD cleavage, or apoptotic protein (CASP8, CASP3, and CASP7) activation." (PMID 33109609, 2020). "Although direct recognition of biofilm’s extracellular Z-DNA by host ZBP1 remains to be confirmed in vivo, ZBP1 plays a pivotal role in inducing inflammatory cell death and type I IFN responses during viral infections." (PMID 41521657, 2026). "ZBP1 has been shown to induce necroptosis mediated by RIPK3 and the downstream effector MLKL, as well as to drive apoptosis in response to viral infections." (PMID 40416961, 2025). "Upon detecting Z-RNA, often produced during viral infections such as influenza, the NLRP3 inflammasome forms a complex with Z-DNA binding protein 1 (ZBP1), which recruits RIPK3 and caspase-8." (PMID 39966334, 2025). "Future studies should address the crosstalk between ZBP1 and CGAS-STING1 in the regulation of PANoptosis during viral infections." (PMID 38932258, 2024). "ZBP1, a PRR that orchestrates both IFNs and inflammatory responses, plays a pivotal role during viral infections." (PMID 39475237, 2024). "Second, in addition to ZBP1 and AIM2, can other nucleic acid sensors also act as scaffold proteins for the assembly of PANoptosome during viral infections?" (PMID 38932258, 2024). "PRV VP22 disrupts the binding between ZBP1 and RIPK3/Caspase-8 and inhibits the cleavage of Caspase-1 and IL-1β induction, thereby promoting viral infection." (PMID 39475237, 2024). "Nucleic acid sensors (e.g., ZBP1 and AIM2) trigger PANoptosis through mediating the assembly of PANoptosomes during viral infections." (PMID 38932258, 2024). "ZBP1-mediated PANoptosis was characterized by NLRP3 inflammasome activation with LDH and IL-1β release during viral infection." (PMID 39850894, 2024). "Thus, different domains of ZBP1 might function synergistically to defend against viral infections." (PMID 38982083, 2024). "In this study, we revealed that PRV VP22, a viral virulence factor, interacted with ZBP1 and suppressed ZBP1-mediated activation of the NLRP3 inflammasome, thereby facilitating viral infection." (PMID 39475237, 2024).
viral infection (continued). "Here, we report that during PRV infection, ZBP1-mediated NLRP3 inflammasome activation is inhibited by the viral tegument protein VP22, thereby facilitating viral infection." (PMID 39475237, 2024). "The interaction between Z-DNA binding protein 1 (ZBP1) and the NLR family pyrin domain-containing 3 (NLRP3) inflammasome has been uncovered in several viral infections." (PMID 39475237, 2024). "OASL chaperones the assembly of RIPK3 and ZBP1 via liquid-liquid phase separation, which induces RIPK3 and necroptosis activation, thereby modulating inflammation and host defence against viral infection." (PMID 36604592, 2023). "Alternatively, microbial or viral infection and cellular stresses that phosphorylates RIPK3 through Z-DNA binding protein 1(ZBP1) or TIR-domain-containing adapter-inducing interferon-β (TRIF)." (PMID 37854679, 2023). "During viral infections, the differential activation of adenosine deaminase acting on RNA 1 (ADAR1) and Z-DNA binding protein 1 (ZBP1) regulate the activity of PANoptosis and innate immune responses." (PMID 37081485, 2023). "More recently, the Zα domains of ZBP1 were reported to be essential for ZBP1-mediated necroptosis, but the precise role of the Zα domains in RIPK3–ZBP1 interactions during virus infection remains elusive." (PMID 36604592, 2023). "PANoptosis represents a combination of pyroptosis, apoptosis, and necroptosis, which is mediated by ZBP1 following IAV infection and other viral infections and inflammation." (PMID 36615244, 2022). "If it is found that pathogenic CoVs do indeed produce Z-RNA (as the ZH3 algorithm predicts) and that the RHIM in Nsp13 regulates ZBP1, RIPK3, RIPK1, TRIF or SMG1 signaling, then we suggest that effects will depend on the stage of viral infection." (PMID 35784331, 2022). "We further focus on Z-DNA binding protein 1 (ZBP1), an emerging innate immune sensor of viral Z-RNAs that regulate programmed cell death pathways and host defense responses during virus infections." (PMID 35587190, 2022). "ZBP1, also known as DAI, was initially identified to induce IFN-mediated MLKL-dependent necroptosis in the context of viral infection." (PMID 34141714, 2021). "ZBP1 and PKZ function as instigators of immune response through sensing of viral nucleic acids following virus infection, via downstream signaling." (PMID 33613567, 2020). "Intracellular dsRNA, evolutionarily a sign of viral infection, can also act as a DAMP, and dsRNA triggers multiple cytoplasmic receptors including ZBP1, MDA5, OAS, and PKR which activate various arms of the innate immune cascade, including NF-κB signaling and the type 1 IFN response." (PMID 40215316, 2025). "Recent studies have reported that RIPK1 kinase activity is not universally required for all necroptosis instances, as RIPK3 can be activated independently of RIPK1 by external stimuli, such as viral infection, heatstroke, and osmotic stress, which activate RIPK3 via Z-DNA-binding protein 1 (ZBP1)." (PMID 40221399, 2025). "Furthermore, ZBP1 induces type-I interferon (IFN-I) response and NF-κB signaling, constituting an important line of defense against viral infections." (PMID 40416961, 2025). "To determine whether RIPK1 binds to ZBP1 during viral infection, we used the FLAG antibody to immunoprecipitate FLAG-ZBP1 from infected HT29-hZBP1 cells." (PMID 39345610, 2024). "Studies in genetic mouse models identified ZBP1 as a potent inducer of inflammation in the absence of viral infection." (PMID 38849574, 2024). "Studies in genetically engineered mouse models revealed an important role of ZBP1 in inducing cell death and inflammation in the absence of viral infection." (PMID 39300211, 2024). "ZBP1, also known as DAI (DNA-dependent activator of IFN-regulatory factors), was previously thought to be one of the cytoplasmic DNA sensors that mediate the activation of the innate immune system against viral infections through IFN." (PMID 37771585, 2023).
viral infection (continued). "Both the in vitro phase-separation assays and the virus infection study collectively show that OASL drives the condensation of RIPK3 and ZBP1 by recruiting them into its liquid droplets via protein–protein interactions, which ultimately induces RIPK3 autophosphorylation." (PMID 36604592, 2023). "ZBP1 is one of the cytoplasmic sensors that regulate cell death and inflammation and initiates the RHIM-dependent activation of RIPK3-dependent necroptosis during virus infections." (PMID 35215199, 2022). "During viral infection or IFN-β treatment, ZBP1 is up-regulated in an IFNAR-dependent manner." (PMID 35587515, 2022). "In this study, ZBP1 was affected by Caspase-8 to induce cell death, which may be mediated via RIPK3, which was obviously different from viral infection." (PMID 36615244, 2022). "Consistent with that, RIPK3 can be activated by associating with other two RHIM-containing adaptor proteins such as TRIF and Z-DNA/RNA binding protein 1 (ZBP1; also known as DAI/DLM-1) to mediate necroptosis by TLR3/4 activation and virus infection, respectively." (PMID 33959729, 2021). "Although Zbp1 has not yet been studied as an atherosclerosis modifier, it has a role as a sensor of viral infections, in NLRP3 regulation after viral infection, and a role in necroptosis and inflammation via its effects on the RIPK1, RIPK3, and MLKL pathways." (PMID 35052410, 2021). "In sum, these results demonstrate that ZBP1 and its ZBDs were required specifically for the induction of necroptosis upon virus infection and not for the induction of an IFN response." (PMID 28716805, 2017). "Finally ZBP1-dependent type I IFN induction—albeit not triggered by B-dsDNA—has recently been reported in some settings of viral infection and autoinflammation." (PMID 37450010, 2023). "IC6mutRHIM virus infection is also cleared in wt mice, but not in ZBP1−/− mice." (PMID 35203445, 2022). "Indeed, consistent with the cell viability assay, RIPK1 co-immunoprecipitated with ZBP1 and RIPK3 in necroptosis-susceptible cells (HT29 WT, mutZα1, and mutRHIMB) following viral infection but was not in cells with inactivating mutations in Zα2 or RHIM A (mutZα2, mutZα1Zα2, and mutRHIMA)." (PMID 39345610, 2024). "Similar to MEF-mZBP1 cells, hZBP1-mRIPK3 complex formation during viral infection is independent of RIPK1 and resistant to 4M treatment, indicating that mRIPK3 tends to form a more stable complex with ZBP1 compared to hRIPK3." (PMID 39345610, 2024). "Notably, treatment with R1-ICR-3 initiated necroptosis in SVEC4-10 and 3T3-SA cells, independent of viral infection, suggesting the inhibitory role of RIPK1 on ZBP1-initiated necroptosis in mouse cells." (PMID 39982916, 2025). "For viral infection-induced necroptosis, RIPK3 and MLKL, but not RIPK1, are required and another protein, Z-DNA-binding protein 1 (ZBP1), also known as DNA-dependent activator of IFN regulatory factors (DAI), functions upstream of RIPK3-MLKL to initiate the formation of the necrosome." (PMID 36703228, 2023). "Unlike ZBP1-Zαβ, full-length ZBP1 could not form LLPS upon virus infection." (PMID 38982083, 2024).
melanoma (34 papers, 2011 to 2026). A malignant, usually aggressive tumor composed of atypical, neoplastic melanocytes. "Small-molecule inhibitors such as curaxin CBL0137 activate ZBP1 to induce necroptosis in cancer-associated fibroblasts and restore immune checkpoint blockade sensitivity in melanoma models." (PMID 40384875, 2025). "The small-molecule curaxin CBL0137 was found to reverse immune checkpoint blockade unresponsiveness in mouse models of melanoma, induce ZBP1-dependent necropsy in cancer-associated fibroblasts, and potently activate ZBP1 by triggering Z-DNA formation." (PMID 38129399, 2023). "This pathway can be activated by the sensor protein ZBP1 and has been shown to repress melanoma growth and improve responsiveness to immune checkpoint blockade." (PMID 41235238, 2025). "ADAR1 inhibits PANoptosis and ZBP1‐mediated immune response, which promotes carcinogenesis in melanoma and colorectal cancer." (PMID 41299204, 2025). "Pharmacological activation of ZBP1 using the small molecule CBL0137 has been shown to restore ICB responsiveness in melanoma." (PMID 41235238, 2025). "Nuclear export inhibitors synergize with IFN-γ to enhance melanoma cell death via ZBP1 upregulation and PANoptotic marker activation." (PMID 40721869, 2025). "Further therapeutic exploration indicated that treating melanoma cells via the activation of ZBP1-induced PANoptosis offers PANoptosis as a critical innate immune biomarker that can be targeted to improve patient outcomes in cancers." (PMID 38169587, 2024). "Mice with a mutation in the ADAR1 gene (Adar1fl/flLysMcre) were resistant to developing colorectal cancer and melanoma, but ZBP1 Zα2 domain deletion restored tumorigenesis in these mice." (PMID 38169587, 2024). "The combination of IFN-γ and the nuclear export inhibitor KPT330, significantly repressed melanoma by inducing ZBP1- and Zα2 domain-dependent PANoptosis." (PMID 38129399, 2023). "High expression of key molecules in PANoptosis such as Zbp1, caspase‐8, and Gsdmd was significantly and positively correlated with the survival probability and prognosis of melanoma patients." (PMID 38069556, 2023). "CBL0137 thereby triggers ZBP1-dependent necroptosis and, in mouse melanoma models, synergizes with immune checkpoint blockade." (PMID 37450010, 2023). "Together, these results indicate that treatments which promote the upregulation of ZBP1 can increase cell death in melanoma cell lines." (PMID 36329783, 2022). "As a therapeutic proof-of-concept, we treated melanoma cells with combination therapy that activates ZBP1 and showed that this treatment induced PANoptosis." (PMID 36329783, 2022). "Indeed, high expression of ZBP1 in melanoma correlates with tumor infiltration by lymphocytes and better prognosis, and similar observations were reported for triple-negative breast cancer." (PMID 37450010, 2023). "Recently, ZBP1 has been found to be involved in the occurrence and development of various tumors, including breast cancer, melanoma, colorectal cancer, non-small cell lung cancer, multiple myeloma, ovarian cancer, urothelial carcinoma, fibrosarcoma, and kidney renal clear cell carcinoma." (PMID 36845119, 2023). "High expression of these genes induces ZBP1‐mediated PANoptosis in melanoma cells." (PMID 38069556, 2023). "Moreover, in mouse models of colorectal cancer and melanoma, cell death driven by Z nucleic acids and ZBP1 limits tumorigenesis." (PMID 37450010, 2023). "Therefore, to study the ZBP1-dependent cell death in cancer cells, we treated the two different melanoma cells lines with nuclear export inhibitors KPT-335 or leptomycin B (LMB) with or without IFN-γ and examined cell death." (PMID 36329783, 2022). "This conclusion is further supported by knocking down of ZBP1 in B16 mouse melanoma tumor model." (PMID 33976222, 2021).